CD4 (CD4 molecule)
Diseases named in the same sentence as CD4 in open-access papers (continued):
Sharing a sentence is not in itself a finding about the gene and the disease.
tumor (continued). "Tumors with high T-cell signatures from our clustering analysis are concordant with high expression of PD-L1, PD-L2, PD-1, CD80, CD86, CTLA-4, Tim-3, LAG3, 4-1BB, CD8, and CD4, EBV-positive status, and low tumor purity and high immune score." (PMID 30911684, 2019). "Anti-CTLA-4 therapy in bladder cancer patients has been demonstrated to decrease Tregs accumulation in the tumor tissue and increase inducible costimulator (ICOS) + CD4+ T cells, which produce IFN-γ and can recognize TAA." (PMID 31443339, 2019). "On the other hand, specific subsets of CD4 T-cells such as regulatory T-cells (Tregs), which are characterized by the expression of the FOXP3 transcription factor, have tumour-promoting activities." (PMID 31434983, 2019). "Subsequently, activated CD4 T helper cells prompt the activation of cytolytic CD8 T cells and B cells for tumor and pathogen elimination in an antigen-specific manner." (PMID 31024913, 2019). "This low frequency, compared with telomerase-specific CD4+ Th1 response, could be related to the use of highly selected and promiscuous HLA class II-binding peptides that cover more than 85% of the population, or to the preferential localisation of these effector cells in the tumour." (PMID 31358938, 2019). "We also compared the levels of different CD4+ T cell subsets between CRC patients presenting with early and advanced stage disease, and between patients who showed varying tumor budding status." (PMID 31921188, 2019). "IHC staining of the tumor samples was performed for immune-related markers, including NF-κB/p65RelA, CD8, CD4, and PD-1." (PMID 31618954, 2019). "Moreover, in vitro re-stimulation of TDLN cells with ovalbumin (OVA) showed increased proportion of IL-17+ CD4+ T cells in Tmem176b−/− compared with WT mice, and in vivo IL-17A blockade showed a clear trend toward suppression of the antitumor effect in tumor-bearing Tmem176b−/− mice." (PMID 31085177, 2019). "The results showed that the expression of MIR155HG in CHOL, HNSC, KIRC, LGG, LUAD, and SKCM was significantly correlated with tumor purity and the infiltration level of immune cells such as B lymphocytes, CD8+ T cells, CD4+ T cells and DCs." (PMID 31568700, 2019). "Baseline levels of tumor-infiltrating CD8+ T cells, CD4 T+ cells and NK cells were shown to be correlated with the likelihood of immune response." (PMID 31164891, 2019). "Anti-PD-1 and anti-CTLA-4 treatments both induce the expansion of specific subsets of tumor-infiltrating exhausted-like T cells, and anti-CTLA-4 additionally engages ICOS+ Th1-like CD4 T cells." (PMID 31182061, 2019). "GBM immune infiltrating cells include lymphocytes (tumor-infiltrating lymphocytes, TILs), the key players of adaptive cellular immune defense, particularly CD8+ T cytotoxic (Tc) and CD4+ T helper (Th)." (PMID 30987226, 2019). "This is the area where CD4+ and CD8+ T cells will exert their cytotoxic antitumor activity as they gain access to viable tumor cells." (PMID 30670061, 2019). "Meanwhile, the combined therapy of anti-PD-1 antibody and Itga2-knockdown increased the populations of tumor-infiltrated CD45+CD8+ T-cells and CD45+CD4+ T-cells further but reduced that of myeloid-infiltrated CD11b+Gr1+ cells in tumors." (PMID 31818309, 2019). "The tumor response of lung metastases a month after SBRT independently correlated with peripheral memory CD4+ T, memory CD8+ T, naïve CD4+ T, and CD4+ naïve/memory ratio." (PMID 31080362, 2019). "T-cell percentages and the balance between CD4+ and CD8+ T-cells up to day 54 post tumor cell injection were comparable to unchallenged mice (data not shown)." (PMID 30972297, 2019). "In particular, tumor-infiltrating lymphocyte (TIL) markers, such as CD4, CD8, CD45RO, and FOXP3, and intratumor budding (ITB) have been identified as markers predicting the pathological response to nCRT in rectal cancer." (PMID 30867256, 2019).
tumor (continued). "Taken together, these studies in both humans and mice identify not only the potential for memory anti-tumor CD4+ and CD8+ T cell development, but also highlight their strong anti-tumor potential." (PMID 31379821, 2019). "Low-dose CUR increased frequency of CD4+ and CD8+ T lymphocytes, in spleens of immunocompetent tumor-bearing mice." (PMID 30959898, 2019). "Here, the authors show that specialized subsets of tumour-infiltrating dendritic cells induce distinct CD4+ T cell programs and specifically identify a CD103–CD11b+ subset which induces tumor-promoting FoxP3– Type-1 regulatory T cells." (PMID 30926808, 2019). "In one study, MHC class I and class II-restricted MART1 tumor peptides loaded onto Dex in acidic conditions bound to MHC molecules with high affinity and activated CD8+ CTL and CD4+ T-cell responses after processing by DCs." (PMID 31615107, 2019). "In immunogenic tumors, SLR14 significantly increases the tumor infiltration of cytotoxic CD8+ T cells, NK cells, and CD11b+ myeloid cells while decreasing the immunosuppressive CD4+FoxP3+ T reg cells." (PMID 31601678, 2019). "Both 19305DP-TCR gene-engineered CD4+ and CD8+ T cells eliminated A*02+NY-ESO-1+ tumor xenografts in NSG mice." (PMID 30626427, 2019). "Experimental depletion of Tregs from the TME results in enhanced infiltration of mature CD4+ and CD8+ T cells into the tumor, leading to tumor rejection." (PMID 31684144, 2019). "The number of Fas+CD4+ T cells and IL-9+CD4+ T cells in tumor tissues was positively correlated, and higher TH9 cell numbers in patients with tumor indicated a better prognosis than lower TH9 cell numbers." (PMID 31266950, 2019). "Despite this, delayed KPC1 tumor outgrowth was observed in the LY364947-treated group and this treatment led to a significant reduction of CD4+ T cells in the tumor microenvironment." (PMID 30959852, 2019). "Our previous work revealed that Plasmodium infection significantly upregulated the population of CD4+, CD8+, and granzyme-producing CD8+ Teff cells in the peripheral blood, tumor-draining lymph nodes and tumor tissues in mice." (PMID 30979375, 2019). "It is believed that once the activated host immune cells (mainly tumor antigen‐specific CD8+ and CD4 +T lymphocytes that have been activated and stimulated) can recognize and destroy tumor cells." (PMID 30950210, 2019). "Of note, inhibiting autophagy resulted in a significant decrease in the frequency of IL-10+ B cells, IL-21+ and IL-10+CD4+ T cells, as well as a significant increase in IFN-γ+CD4+ T cells, in the tumor-draining lymph nodes and tumor tissue." (PMID 31300052, 2019). "We analyzed core biopsies from 87 pre-therapeutic BC patients for total TILs and the following subtypes: CD3+, CD4+, CD8+, CD20+ and CD68+ cells in correlation to clinicopathological parameters and disseminated tumor cells (DTCs) in the bone marrow." (PMID 30717704, 2019). "The ability of cytotoxic CD4+ T cells (CD4-CTLs) to directly kill MHCII+ targets expressing cognate Ag in vitro has raised significant interest among viral and tumor immunologists alike." (PMID 31308093, 2019). "The analyses revealed post-treatment persistence and activity of tumor-infiltrating NK cells (CD3−/NK1.1+), NKT cells (CD3+/NK1.1+) and CD4+ T cells, and a general enrichment of total leukocytes in the treated tumors." (PMID 30728358, 2019). "Our results show the potential of this cDC1-based vaccine to be combined with standard anti-PD-1 therapy or used in anti-PD-1 resistant tumors, inducing both effector and long-lasting anti-tumor CD8+ and CD4+ T cell responses." (PMID 30961656, 2019). "At this time point, tumor size and frequency of total or PD-1-expressing CD8+ and CD4+ T cells, as well as OVA-specific CD4+ T cells in the tumor was equal." (PMID 30961656, 2019). "Research over the past two decades has revealed that CD4+ effector T cells, especially IFN-γ-producing T helper 1 (Th1) cells, can exhibit anti-tumor activity." (PMID 31300052, 2019).
tumor (continued). "Following TfR-BiTE-mediated tumor lysis, both CD8 and CD4 T-cell subsets maintained an activated phenotype as shown by expression of the early activation marker CD69 and cytotoxic granule granzyme B (GrB)." (PMID 31293575, 2019). "(D) CD8 and (E) CD4 T cells isolated from CCSP-rtTA; TetO-EGFRL858R tumor bearing mice untreated or treated with erlotinib." (PMID 31291990, 2019). "The following hypothetical mechanisms were considered to explain the phenomenon: changes in tumor microvessel formation (CD31), tumor proliferation (Ki67), tumor apoptosis (TUNEL), the NK cell response (NCR1) or the T lymphocyte response (CD8 and CD4)." (PMID 31391111, 2019). "A DNA-based vaccine approach demonstrated that CD248 can be effectively targeted immunologically; anti-tumor responses were generated in several mouse models; and CD8+/CD4+ T cell responses were elicited against peptides derived from CD248 protein." (PMID 30847027, 2019). "Further studies have revealed that they efficiently induce neoantigen-specific CD4+ T cells, activate tumor-reactive CD8+ T cells, and promote the polarization of naïve CD4+ T lymphocytes into Th1 or Th17/Th1 cells." (PMID 30984181, 2019). "Significant activation of immune cells was observed in the Comb group, with an increase in CD8+/GzmB+ tumor-infiltrating lymphocytes (TILs) in the irradiated tumor, and of CD8+/GzmB+ and CD4+ TILs in the unirradiated tumor, respectively." (PMID 30774761, 2019). "Much higher frequencies of CD4+CD25+CD127–Foxp3+ Tregs were detected in OPSCC tissue compared to PBMC, indicating their tumor-specific accumulation." (PMID 30658697, 2019). "Our results suggest that in patients with high CD4/Treg ratios, the immune response was more strongly activated after SABR, thereby resulting in improved tumor regression." (PMID 30971280, 2019). "At day 24 the DR500 suppressive effect on Gr1+CD11b+ cells disappeared and the inductive effect on CD4+, CD8+ T and B lymphocytes was attenuated at all sites, particularly in the primary tumor, compared to MR20-injected mice." (PMID 30546090, 2019). "HSD fed animals further displayed a higher percentage of CXCR3+ CD4+ T cells in mLN cells, indicative of an increase in TH1 cells in HSD fed tumor-bearing animals." (PMID 31214164, 2019). "In the same co-culture experiments, the IFNγ secretion assay for CD4+ and CD8+ T cells showed some relationships among peripheral blood, normal lung tissues, and tumor tissues." (PMID 30796310, 2019). "We characterize the phenotype of EpCAM+ CD4+ T cells as PD-L1+ CCR5+ CCR6+ and further confirm that this subset also increases in tumor microenvironments with irregulated p38 MAPK signaling pathway." (PMID 31354723, 2019). "In contrast, overexpression of miR-34a in EBNA2-expressing U2932, in the presence of CD4/CD8 cells, induced significant tumor cell death, as indicated by increased caspase-3 expression (Fig. 6bii, c)." (PMID 29946193, 2019). "Tissue-localizing HPV-specific CD4 and CD8 T cells are also potentially important to tumor regression." (PMID 31555284, 2019). "In the process of defining the specificity of the anti-tumor immune response, MHC-II type molecules present antigens, which are recognized by CD4 + T cells." (PMID 31443694, 2019). "Taken together, although CD4+ and CD8+ T cells were shown to be able to recognize CLL tumor cells, functional modulation by the tumor clone leads to inhibition of T-cell-mediated immune responses and inadequate tumor control." (PMID 31484424, 2019). "UAMC-1110 significantly increased tumor infiltrating CD8+ T cells, including effector subpopulations (Fig 3Bii and data not shown), while combination UAMC-1110 and radiation increased CD4+ T cells, including regulatory T cells (Fig 3Biii-iv)." (PMID 30726287, 2019). "CD4- and FOXP3-stained images were used to identify T-helper cell and Treg cell distribution in the tumor microenvironment." (PMID 31635338, 2019).
tumor (continued). "(B) Quantification of GzmB+ CD4 and CD8 T cells after PMA/ionomycin stimulation and intracellular cytokine staining of cells in the lungs of tumor bearing CCSP-rtTA; TetO-EGFRL858R mice in the absence (−) and presence (+) of erlotinib for 2 weeks." (PMID 31291990, 2019). "Tumor nodules were then digested and analyzed by flow for the presence of CEA, CD45 lymphocytes, CD4 or CD8 T-cells, and Ly6G neutrophils or F4–80 macrophages." (PMID 31488104, 2019). "The T helper cells (Th cells), also known as CD4+ cells, show a heterogenous class of T-cells and help the response of TCD8+, particularly in the initial stages of tumor progression." (PMID 31771178, 2019). "The 11-mer peptide allowed for the stimulation of CD4+ T cells, that have been shown, in addition to providing help to CD8+ CTLs, to mediate potent anti-tumor, HLA class II-mediated, cytotoxic responses in vivo." (PMID 30783516, 2019). "Comparable numbers of CD4+, CD8+, FOXP3+ and GrB+ cells were observed at the tumor microenvironment in the 46 patients series." (PMID 31481738, 2019). "To test the intrinsic capacity of CD4 T cells, CD8 T cells and NK cells to react toward tumor spheroids we purified and cocultured them, alone or combined, with HT29 tumor spheroids." (PMID 30871626, 2019). "Various immune cell subsets, including CD4+ and CD8+ lymphocytes, NK cells, granulocytes, macrophages, and dendritic cells, are then recruited around the tumor area and exhibit immunologic reactions against the cancer cells." (PMID 30608942, 2019). "B. Individual tumor volume follow-up in groups of mice intratumorally treated with with BO-112 or vehicle and depleted from CD8+, CD4+ or NK1.1+ cells separately or concomitantly." (PMID 31046839, 2019). "This suggests that CD4+ T cell help promotes CTL responses through the recruitment of functional CD8+ T cells primed by DCs and capable of migrating into the tumor." (PMID 31379821, 2019). "Even more significant than a reduction in CD4+ and CD8+ T cell numbers in Stat4−/− tumor bearing mice, was the strikingly elevated expression of the immunosuppressive markers PD-1 and TIM3 on splenic CD4+ and CD8+ T cells." (PMID 32010142, 2019). "Our results are in agreement with the finding that the numbers of conventional Treg (CD4+CD25+) cells were increased in spleens of tumor-bearing mice, while electroporation reduced the number of these cells to a level comparable with tumor-free mice." (PMID 31717542, 2019). "This modulation occurs through preferential depletion of stromal cells which suppress and neutralize robust anti-tumor immune responses, such as myeloid cell populations and Tregs, while effector CD8+ and CD4+ T-cells and NK cells are relatively spared." (PMID 31379850, 2019). "Immune cell populations analyzed include CD11b+/F4/80+ macrophages (a), CD4+ T cells (b), CD8+ T cells (c), PDGFRα fibroblasts (d), and tumor cells (e)." (PMID 30990165, 2019). "TOX is a transcription factor involved in CD4+ T-cell development with downstream effects on RUNX3, a known tumor suppressor gene." (PMID 31139323, 2019). "In cHL lymph nodes, the tumor bulk mostly comprises CD4+ and cytotoxic T cells, B cells, macrophages, and other cell types that crosstalk with the few “Hodgkin Reed-Sternberg” (HRS) tumor cells." (PMID 31399034, 2019). "Immunological analysis showed an overall increase of CD4+ and CD8+ T cells in the peripheral blood and a positive tumor antigen-specific ELISPOT analysis in two of ten patients." (PMID 31020037, 2019). "In the univariate analyses, high CD8+CD28+ T-cell counts (OR 0.12, 95% CI 0.03–0.48; P = 0.003), CD4/Treg ratio (OR 0.24, 95% CI 0.06–0.90; P = 0.035), and BED10 (OR 0.91, 95% CI 0.84–0.99; P = 0.032) predicted tumor response to SABR." (PMID 30971280, 2019). "Natural tumor antigen-loaded cDC1s were transferred and their potential for induction of endogenous CD8+ and CD4+ T cell responses in vivo, cancer prevention and therapy were assessed in three grafted cancer models." (PMID 30961656, 2019).
tumor (continued). "This is consistent with our previous experience in a preclinical study, which showed that transient depletion of CD4+ cells expands CD8+ T cells and shifts the tumor microenvironment toward type I immunity." (PMID 31340866, 2019). "In multivariate logistic regression analysis, memory CD4+ T and CD8+ T were independent predictors of tumor response to SBRT, consistent with the function of memory cells." (PMID 31080362, 2019). "The immune response was measured by gene expression of characteristic T-cell and B-cell markers, including CD4, CD8, and PD-1 T-cell markers, and tumor purity, which when low indicates high immune cell infiltration into the tumor microenvironment." (PMID 30911684, 2019). "In order to further analyze the mechanistic effect of the tumor protection, CT26 challenged mice were vaccinated and additionally injected with CD4+ or CD8+ depleting antibodies." (PMID 30858929, 2019). "The leucocytes in the mimic distant tumours were collected and co-stained with CD3, CD4 and Foxp3 for further analysis." (PMID 31048681, 2019). "The frequency of total CD4+ Tconv cells and CD8+ T cells in tumor-draining lymph nodes was increased by combination treatment." (PMID 31921384, 2019). "Conversely, CD4+ FOXP3+ Th2 cells, M2 macrophages, and myeloid-derived suppressor cells (MDSCs) can drive tumour growth." (PMID 31527531, 2019). "In mice injected with CEA‐positive tumor cells, the number of T cells and the ratio of CD8 T cell to CD4 T cell in CEA‐CAR‐T cell in combination with rhIL‐12 treatment group was higher than CEA‐CAR‐T cell treatment group." (PMID 31237116, 2019). "Depletion of MDSCs in HFD mice reverts tumor growth rates to that observed in LFD mice and restores antigen-driven T cell activation, while depletion of both MDSCs and CD4+ and CD8+ T cells increases tumor growth rate." (PMID 31156644, 2019). "Compared to the control group, we found that IR-780 treatment clearly increased the infiltration of both CD4+ and CD8+ T cells into tumor tissues." (PMID 31781498, 2019). "Many researchers have analyzed its cellular composition (CD4, CD8, Tregs, NK cells, TAMs, etc.)and secretion of molecules involved in tumor growth (e.g., cytokines, chemokines, cytokine receptors) and immunosuppression (e.g., PD-1, PD-L1, IDO, MHC-I, MHC-II)." (PMID 31096713, 2019). "The results support a regulatory role for CD5 in DC in the context of proliferation of CD4+ and CD8+ T cells and demonstrate that blockade of CD5 signals in DC enhances anti-tumor immune responses." (PMID 31491023, 2019). "CAELYX® alone decreased the number of CD4+ T cells inside the tumor parenchyma, while CAELYX® and LTX-315 alone induced a significant increase in tumor-infiltrating CD8+ T cells." (PMID 30670061, 2019). "Second, high densities of CD4+ and CD8+ T cells in tumor tissues have been found to be favorable prognostic factors in NSCLC patients." (PMID 31602260, 2019). "An increased number of tumor infiltrating T cells was found in subcutaneous prostate tumors from GPR68 KO mice; depleting CD4 or CD8 T cells led to tumor rejection." (PMID 30696114, 2019). "The finding was consistent with the well-established cooperative role of CD4+ and CD8+ T-cells in tumor eradication." (PMID 30828566, 2019). "The mice rejecting the tumor were immune to MHC-II-negative parental tumors and their CD4+ TH cells protected naïve H-2b C57Bl/6 mice in adoptive cell transfer experiments." (PMID 31417570, 2019). "The levels of CD4+CD25+ cells in PEF2 and PEF2 + Ca-treated mice were lower than in tumor-bearing controls, but higher than in tumor- free mice (average of 4% in tumor-free mice, 6.9% in tumor-bearing mice and around 4% in PEF2 and PEF2 + Ca-treated mice)." (PMID 31717542, 2019). "In order to demonstrate that Tregs are biologically active in CCK168 tumors, and limit tumor eradication by α-PD1, we depleted CD4 + CD25+ Tregs using an α-CD25 antibody engineered to optimize intra-tumoral ADCC of CD25+ Tregs." (PMID 30832732, 2019).